DCN (decorin)
Diseases named in the same sentence as DCN in open-access papers (continued):
Sharing a sentence is not in itself a finding about the gene and the disease.
lung fibrosis (continued). "Surprisingly, these data are consistent with a rat model investigating bleomycin-induced pulmonary fibrosis, which showed that biglycan production was increased early in the fibrotic process and declined over time, while decorin production was enhanced later in this process." (PMID 20459817, 2010). "On these bases, decorin targeted therapy approaches have been proposed to treat fibrosis in wound healing (Järvinen, 2012; Järvinen and Ruoslahti, 2010, 2013), liver fibrosis and possibly for other tissue fibrosis (Järvinen, 2012) including pulmonary fibrosis." (PMID 33409282, 2020). "Pulmonary fibrosis was also modeled in mice by subcutaneous bleomycin administrations (under light isoflurane anesthesia), and the effects of receptor antagonists on tissue density, collagen‐producing cells, myofibroblasts and decorin expression were investigated." (PMID 27482070, 2016). "The antifibrotic properties of eggshell membrane components, particularly via decorin-mediated inhibition of TGF-β signaling and YAP/TAZ pathway modulation, have been discussed in recent reviews on pulmonary fibrosis." (PMID 41009682, 2025). "Their analysis highlighted the expression of profibrotic genes DCN and JUN (C12 and C9, respectively): DCN modulates TGFβ‐driven fibrosis in a number of organs and JUN induction drives murine pulmonary fibrosis." (PMID 38685679, 2024). "In conclusion, ESM enhances the secretion of antifibrosis mediator DCN from fibroblasts, ameliorates BLM-induced pulmonary fibrosis, and suppresses the TGF-β-dependent fibrosis signaling pathway TAZ in vitro and in vivo." (PMID 39234595, 2024). "As discussed under the “TGFβ signaling pathway,” soluble decorin is an endogenous ligand to TLR2 and TLR4 and can activate the p38 MAPK and ERK pathways, promoting inflammation and lung fibrosis and acting as a DAMP." (PMID 36835058, 2023). "Thus, we demonstrated that MSCs play a role in the treatment of BLM-induced pulmonary fibrosis through the TGF-β1/Smad7 pathway and that MSCs overexpressing DCN showed better efficacy." (PMID 40438789, 2025). "This suggests that DCN-overexpressing MSCs play a significant role in regulating macrophage polarization, which may be a key pathway for MSC treatment of pulmonary fibrosis." (PMID 40438789, 2025). "Decorin (DCN) blocks TGF-β signaling in pulmonary fibrosis, although there are no cellular pharmacological methods to stimulate DCN secretion." (PMID 39234595, 2024). "Decorin could enhance pulmonary function during SARS-COv-2-related problems, such as lung fibrosis." (PMID 39906348, 2024). "On the other end, in its soluble form, decorin is an endogenous ligand to TLR2 and TLR4 and can activate the p38 MAPK and ERK pathways, leading to pro-inflammatory signaling; it may also promote lung fibrosis when degraded by cathepsin-S because fragmentation disrupts its anti-fibrotic capabilities." (PMID 36835058, 2023). "Given that PGs are co-distributed with collagens in the ECM, and that small PGs such as decorin are critical for collagen deposition and integration into the ECM, inhibition of PG synthesis by 4-MU4-deoxy-xyloside may influence the assembly of the ECM fibrils during lung fibrosis." (PMID 26751072, 2016).
lung cancer (16 papers, 2011 to 2026). A malignant neoplasm involving the lung. "We next analyzed the effect of FAM20B mutations on the synthesis of decorin in human lung cancer cell line A549, which abundantly produced this PG in the medium." (PMID 40422215, 2025). "Low levels of decorin are present in invasive breast carcinomas and this trait is associated with poor outcome in breast and lung cancer patients." (PMID 23029096, 2012). "Another study reported plasma DCN levels to be lower in patients with oesophageal squamous cell carcinoma than in controls, and similar findings were seen in a smaller study on non‐small cell lung cancer." (PMID 41392017, 2026). "Multiple studies have suggested that DCN can suppress lung cancer progression by blocking receptor tyrosine kinases." (PMID 34869590, 2021). "The group of Biaoxue R found that decreased expression of DCN correlates with lymphatic metastasis in patients with lung cancer." (PMID 32519739, 2020). "CTSS-degraded decorin is also being investigated as a potential biomarker for fibrotic lung disorders including IPF in addition to lung cancer." (PMID 32398133, 2020). "DCN-CS was elevated in lung cancer patients (p < 0.0001) and IPF patients (p < 0.001) when compared to healthy controls." (PMID 28793886, 2017). "DCN-CS were measured in serum samples from three independent cohorts including patients with lung cancer, IPF, COPD and healthy controls." (PMID 28793886, 2017). "The clinical data indicated that degradation of decorin by cathepsin-S is an important part of the pathology of lung cancer and IPF." (PMID 28793886, 2017). "The data suggest that Cat-S specific degradation of decorin has a relevant role in the pathology of lung cancer and IPF." (PMID 28793886, 2017). "Based on the high elevated level of degraded decorin in patients compared to healthy controls, the present assay can provide a novel non-invasive clinical tool in lung cancer and IPF." (PMID 28793886, 2017). "Several previous studies reported SLRP proteins in breast, pancreatic, colorectal, uterine cervical, prostate, and lung cancers, among others, highlighting the controversial roles of DCN and LUM in cancer biology." (PMID 26230845, 2015). "Interestingly, high expression of DCN, LAMA2, and ELN in lung cancer is associated with better survival." (PMID 37848457, 2023). "Moreover, decreased DCN expression correlates with lymphatic metastasis in patients with lung cancer." (PMID 34869590, 2021). "Decorin, a proteoglycan of the interstitial matrix, is degraded by CTSS in lung cancer and may be associated with lung cancer pathology." (PMID 32398133, 2020). "Multiple studies have suggested that DCN can suppress lung cancer progression." (PMID 32519739, 2020). "The fact that the AUC was higher for lung cancer compared to IPF, suggests that this pathological event seems to be more associated with lung cancer than IPF and DCN-CS could serve as a potential diagnostic biomarker for lung cancer." (PMID 28793886, 2017). "Furthermore, some investigators suggest that decorin and lumican inhibit tumor growth, particularly in prostate and lung cancer." (PMID 28789706, 2017). "The level of DCN-CS was significantly higher in patients with lung cancer and IPF compared to healthy controls, suggesting a pathological role of degraded decorin in these lung disorders." (PMID 28793886, 2017). "Skeletal muscle metastases from lung cancer are rare; indeed, in the later stages of cancer with tumour-promoting TGF-β, decorin, which is enriched by skeletal muscle contraction, may sequester TGF-β." (PMID 41300368, 2025).
lung cancer (continued). "Decreased levels of decorin in NSCLC tissue samples, particularly ADC cases, indicate that decorin could play a role in lung cancer carcinogenesis." (PMID 22104218, 2011). "The main findings of this study were: 1) the fragment was significantly elevated in lung cancer and IPF patients compared to healthy controls 2) the fragment was detectable in serum and 3) the assay was technically robust and specific towards a unique Cat-S degraded fragment of decorin, DCN-CS." (PMID 28793886, 2017).
osteosarcoma (16 papers, 2010 to 2024). A usually aggressive malignant bone-forming mesenchymal neoplasm, predominantly affecting adolescents and young adults. "Very recently, the reduced DCN expression has been linked to osteosarcoma development in Li-Fraumeni syndrome (LFS)." (PMID 26697491, 2015). "It was found that H19 mediates suppression of LFS-associated osteosarcoma formation through DCN." (PMID 26697491, 2015). "DCN can not only inhibit osteosarcoma cell-mediated angiogenesis, but also the lung metastasis of osteosarcoma in mice." (PMID 36387908, 2022). "DCN expression by osteosarcoma cells, in turn, inhibited their capability to send distant metastases to the lungs." (PMID 26697491, 2015). "For instance, decorin was shown to slow the migration rate of osteosarcoma cells by a mechanism depending on its CS/DS chain, while CS/DS-PGs biglycan and decorin, independently of their CS/DS, increased mobility of lung fibroblasts." (PMID 23843960, 2013). "While in most studies DCN has been found to have an antioncogenic role, others correlate DCN with increased migration of human osteosarcoma cells and high expression in endothelial cells undergoing angiogenesis." (PMID 22363530, 2012). "It is interesting to note that in osteosarcoma cells, decorin was also found to be necessary for cell migration." (PMID 21958730, 2011). "Osteosarcoma cells were shown to be insensitive to decorin-induced growth arrest, rather decorin seemed to be beneficial, since it was necessary for osteosarcoma cell migration." (PMID 21958730, 2011). "Moreover, in patients with Li-Fraumeni syndrome, DCN (decorin) mediated Li-Fraumeni syndrome related osteosarcoma." (PMID 34828292, 2021). "Moreover, DS‐bearing decorin was 20‐fold more effective than CS‐bearing decorin in inhibiting the mobility of osteosarcoma cells." (PMID 30637950, 2019). "Previously decorin has been shown to be able to suppress also lung metastasis in osteosarcoma." (PMID 28653173, 2017). "However, under certain circumstances some cancer cells, e.g. cancers of blastoma origin or osteosarcomas have been shown to be able to express decorin." (PMID 28653173, 2017). "Moreover, these Osteosarcoma cells have also been shown to constitutively produce decorin and manifest resistance to decorin induced growth arrest." (PMID 21958730, 2011). "However, studies by us and others have shown that decorin is expressed by oral squamous cell carcinoma and osteosarcoma cells." (PMID 21958730, 2011). "Interestingly, a recent study demonstrated that decorin-coated titanium substrates abolished the oncogenic potential of osteosarcoma cells but, on the other hand, stimulated the proliferation of pre-osteoblasts, suggesting that decorin exerts specific antitumor action." (PMID 34069554, 2021). "Second, the specific mechanisms of DCN and P4HA1 in osteosarcoma were still unclear." (PMID 33816483, 2021). "The authors first looked at the expression of decorin in multiple myeloma cells and found that when compared to an osteosarcoma cell line that constitutively expressed decorin, multiple myeloma cells had no detectable amounts of decorin." (PMID 31330786, 2019). "In oral malignant squamous cell carcinoma cells, the nuclear localization of DCN seems to enhance cellular invasion via the nuclear epidermal growth factor receptor (EGFR) pathway, whereas in osteosarcoma cells, DCN-mediated growth arrest is avoided via the protracted activation of membrane EGFR." (PMID 26230845, 2015).
pancreatic cancer (16 papers, 2013 to 2026). "Another study has also described stage-related accumulation of decorin during progression of laryngeal and pancreatic cancer, also associated with tumour-specific post-translational modifications." (PMID 24142880, 2013). "The aim of this study was to further explore the potential clinical significance of DCN in pancreatic cancer, both regarding its dynamics in serum during chemotherapy and its compartmental and cellular distribution in tumour tissue." (PMID 41392017, 2026). "In this study, we constructed a subcutaneous tumor model of pancreatic cancer and applied a combination of Decorin-carrying oncolytic adenoviruses and chemotherapy for in vivo and in vitro experiments." (PMID 41924602, 2026). "In pancreatic cancer cells, proteoglycan decorin (DCN) released by ferroptosis triggers innate and adaptive immune responses." (PMID 39769097, 2024). "Cells in ferroptosis release proteoglycan decorin (DCN) dependent on autophagy, leading to pro‐inflammatory pathology, and the inhibition of DCN release limits the ability of pancreatic cancer cells in ferroptosis to induce a cancer‐protective immune response." (PMID 37860928, 2023). "Earlier in vitro studies showed that reduced decorin expression facilitates tumorigeneses and growth of breast, ovarian, and pancreatic cancers, among others." (PMID 32155897, 2020). "TGF-β1 and CM from pancreatic cancer cells synergistically suppressed decorin and lumican, and stimulated versican expression in pancreatic stellate cells." (PMID 25593993, 2014). "Additionally, we have utilized Syrian hamster pancreatic tumor model for the evaluation of RdB/IL12/DCN in combination with ICIs (αPD-1, αPD-L1, or αCTLA-4)." (PMID 40335925, 2025). "Decorin is a small lysine-rich proteoglycan found in the extracellular matrix, that has been shown to inhibit tumour growth in many cancers, including pancreatic cancer, via interactions with the epidermal growth factor receptor and other members of the ErbB family." (PMID 37936126, 2023). "Decorin gene therapy was successfully applied in models of prostate and pancreatic cancers as well." (PMID 32477937, 2020). "Similarly, a neurotensin peptide-conjugated polyethylene glycol (PEG-NT)-coated OAd was engineered to express both decorin (DCN) and a soluble Wnt decoy peptide sLRP6E1E2 (oAd/DCN/LRP-PEG-NT) specifically targeting pancreatic cancer." (PMID 39337402, 2024).
asthma (15 papers, 2006 to 2024). "In another study, decorin deficiency inhibited the inflammatory reaction in a mouse model of allergen-induced asthma." (PMID 25781946, 2015). "Further comparison of the expression of marker genes in all cell subtypes in control and asthma revealed marker genes like DCN, COLOA1, COX4L2, CLEC3B, EPAS1 and POSTN belonging to stromal cells remained the most variable genes." (PMID 36439114, 2022). "Herein, we establish a mechanistic link between asthma and gliomagenesis by demonstrating that asthma induces decorin expression in T cells to reduce microglia support of Nf1 optic glioma growth." (PMID 34880260, 2021). "They attributed this failing to a reduced expression of decorin (a proteoglycan that is required for normal spacing of collagen fibrils within fibers) by airway fibroblasts from subjects with asthma." (PMID 30985216, 2019). "At present, the postulated mechanism whereby reduced fibroblast decorin expression drives disorganized airway collagen in patients with asthma remains primarily correlative and needs to be proved experimentally." (PMID 30985216, 2019). "Future studies should seek to manipulate decorin levels in murine models of allergic airways disease and primary patient cells to validate that they impact collagen organization and ultimately asthma pathophysiology." (PMID 30985216, 2019). "In the alveolar parenchyma, patients with uncontrolled asthma had increased percentage areas of collagen, versican and decorin compared to patients with controlled asthma." (PMID 24950767, 2014). "In central airways we found increased percentage areas of versican and decorin in patients with uncontrolled asthma compared to both healthy controls and patients with controlled asthma." (PMID 24950767, 2014). "This location is also abundant in fibroblasts and myofibroblasts in the asthma patient, while the proteoglycans, versican, biglycan, and decorin, accumulate in the submucosa below the epithelium in bronchial biopsies from asthma patients." (PMID 21658209, 2011). "In postmortem lung tissue from patients dying with fatal asthma, hyaluronan, versican, biglycan and decorin were prominently localized in the airway wall." (PMID 16643666, 2006). "They demonstrated that asthma induces the expression of decorin (a proteoglycan) on T cells." (PMID 38557942, 2024). "Additionally, there were increases in the number of cells positive for ROCK1, ROCK2, TGF-β, MMP-9, MMP-12, and TIMP-1, and the percentages of isoprostane, biglycan, decorin, fibronectin, and collagen fibers, in the asthma group." (PMID 30979017, 2019). "The increase in decorin expression in patients with severe asthma, could be a protective mechanism for modulating pulmonary remodeling." (PMID 30979017, 2019). "In this aspect, one can speculate that the increase in decorin expression in patients with uncontrolled asthma could be a protective mechanism to mitigate remodeling." (PMID 24950767, 2014). "Further studies are therefore necessary to determine whether inhibition of decorin would be beneficial in asthma." (PMID 20300191, 2010). "Versican, a large aggregating proteoglycan essential for regulating the lung’s viscoelastic properties and decorin, a small leucine-rich proteoglycan that interact with TGF-β and regulate collagen fibril spacing, have both been implicated in increased bronchial tissue remodeling in asthma." (PMID 39068387, 2024). "Thus inhibition of decorin could have potentially beneficial and detrimental effects in asthma depending on the dominant mechanisms of action." (PMID 20300191, 2010). "The increased amount of myofibroblasts in the alveolar parenchyma of patients with uncontrolled asthma could be linked to the increased expression of EDA-fibronectin, and is in accordance with our finding of an increased percentage area of several matrix components such as collagen and decorin." (PMID 24950767, 2014).
asthma (continued). "After application of maximal strain, there was increased mRNA expression of key proteoglycans, versican and decorin, in asthma-derived compared to non-asthma-derived bronchial fibroblasts." (PMID 39068387, 2024). "As observed in the experimental models of asthma (OVA and HDM induction) where decorin expression was induced in T cells, decorin treatment of Nf1OPG mice reduced tumor proliferation (%Ki67+ cells), with no change in optic nerve volumes, microglia (Iba1+ cells), or T cells (CD3+ cells) in vivo." (PMID 34880260, 2021). "Relevant to the human condition, DCN expression was also increased in CD4+ and CD8+ T cells from patients with non-steroid-dependent asthma relative to healthy controls (GSE31773)." (PMID 34880260, 2021).